STAT3 (signal transducer and activator of transcription 3)
Diseases named in the same sentence as STAT3 in open-access papers (continued):
Sharing a sentence is not in itself a finding about the gene and the disease.
tumor (continued). "Recent clinical data further suggest that agents regularly used in the therapy of RCC may elicit their anti-tumor effect via targeting the STAT3 pathway." (PMID 22899991, 2012). "Studies show that STAT3 are constitutively activated and abnormally expressed in tumor tissues and cell lines, and promote tumor proliferation, differentiation, invasion, metastasis, angiogenesis and immune escape by modulating the downstream genes livin and caspase-3." (PMID 23110625, 2012). "In addition, EEHDW treatment suppressed STAT3 phosphorylation in tumor tissues, which in turn resulted in the promotion of cancer cell apoptosis and inhibition of proliferation." (PMID 22754353, 2012). "Given the significant decrease in the vascularity of AZD1480- treated tumors and consequent tumor necrosis, we suggest that phospho-STAT3 inhibition in the microenvironment (endothelial cells) cooperates with RET inhibition in cancer cells to induce tumor regression." (PMID 23056499, 2012). "STAT3 inhibition has a clear anti-tumour effect as demonstrated by a variety of reagents." (PMID 22689141, 2012). "Our laboratory previously characterized constitutive STAT3 activation in primary canine OS tumor samples and canine OS cell lines, and showed that direct downregulation of STAT3 protein expression in OS lines using siRNA induced loss of cell viability and apoptosis." (PMID 23244668, 2012). "Besides increasing cell motility and invasion, STAT3 is also thought to upregulate the expression of anti-apoptotic and growth-promoting genes and to facilitate the colonisation of the liver by tumour cells." (PMID 23157946, 2012). "AZD1480 decreased total tumor p-STAT3 cells and this was most evident in the macrophage population." (PMID 23013619, 2012). "Inhibiting STAT3 activity reduces conversion of Foxp3-negative T cells to tumor-associated Tregs and increases CD8+ T cell infiltration in tumor - a strategy that has been used to inhibit primary tumor growth." (PMID 22911830, 2012). "Studies show that many cytotoxic drugs induce tumor cell apoptosis by inhibiting STAT3, indicating STAT3 might be a new target for cancer therapy." (PMID 23110625, 2012). "Interestingly, HCMV-US28 was found to be expressed in GBM tissue sections and GBM patients that had high grade phosphorylated STAT-3 (pSTAT-3) in their tumors had shorter time to tumor progression and overall survival." (PMID 22424569, 2012). "Further characterization of these macrophages demonstrated that they expressed p-STAT3 indicating a M2 tumor-supportive phenotype and that cediranib and AZD1480 in the combination treated group was preferentially reducing this subpopulation (i.e. M2 immune suppressive macrophages)." (PMID 23013619, 2012). "The control group had the largest average tumor weight (1.78 g), followed by the group that received control siRNA before receiving Src+STAT3 siRNA (0.96 g), the Src+STAT3 group (0.52 g), and the Src+STAT3+Myc group (0.41 g), and these measurements agreed well with the tumor size measurements." (PMID 21541295, 2011). "It is therefore plausible that the STAT3-Hsp interactions may be one such survival pathway that allows tumour cell survival, growth and metastasis in cancers." (PMID 21152185, 2011). "In light of the finding that STAT3 may be alternately protumorigenic or suppressive to tumor growth, additional research is needed to elucidate the role of STAT3 in a variety of genetic contexts, including the background genotype of the host." (PMID 22190972, 2011). "Inhibiting STAT3 by AG490 induces anti-tumor activity via activation of STAT1 and autophagy." (PMID 21931823, 2011). "The theory that STAT3 may exert tumor-suppressing effects in GBM originated from the observation that STAT3 plays a prominent role in astrocyte differentiation." (PMID 22190972, 2011).
tumor (continued). "A previous study showed that loss of Smad4expression in PDA can lead to the aberrant activation of STAT3, which may contributeto the switch in function of TGFβ from a tumor-suppressive to a tumor-promotingEMT pathway in PDA." (PMID 21572519, 2011). "Recent studies have also indicated that STAT3 activation contributes to tumor immune evasion." (PMID 22046235, 2011). "The use of pharmacological agents to inhibit STAT3 activity may lead to a rebalancing of the signaling pathways regulating cell growth and lead to inhibition of tumor progression." (PMID 22046235, 2011). "In addition, MMP-1 and MMP-9 were found to be regulated by STAT3, which plays a crucial role in tumor invasion and metastasis." (PMID 21991388, 2011). "Furthermore, tumor invasion into the vessel and muscle was more frequent in the control tumors than STAT3-silenced tumors." (PMID 21991388, 2011). "Thus, the disruption of tumor angiogenesis resulting from the inhibition of STAT-3, HIF-α/VEGF/Rho-GTPases, and MMPs production represents a promising strategy for cancer therapy." (PMID 22016776, 2011). "Treatment of either CD33+ or CD11b+ tumor-cell line-induced MDSC with lipopolysaccharide, a known activator of MDSC function, caused further up-regulation of STAT3, C/EBPβ, and HIF1α concurrent with increased expression of ARG-1, iNOS, and NOX2-component NCF1 (data not shown)." (PMID 21658270, 2011). "However, when compared to the MSC/Adv-Stat3(-) group, the tumor growth in the Adv-Stat3(-) groups tended to be larger." (PMID 22054049, 2011). "Meanwhile, STAT3-siRNA significantly reversed tumor invasion by IL-17 stimulation in HCC." (PMID 22171994, 2011). "Since S3DN expression correlated with suppression of tumor invasion, we sought to determine whether it altered the levels or subcellular localization of active Stat3 in tumors." (PMID 21595927, 2011). "A high level expression of STAT3 mRNA was observed in tumor samples." (PMID 21575192, 2011). "It suggests MSCs could carry a sufficient amount of Adv-Stat3(-) to the tumor sites before they were lysed by the virus." (PMID 22054049, 2011). "In addition to inhibiting tumor growth through tumor oncolysis and suppressing the Stat3 pathway, MSC/Adv-Stat3(-) treatment notably increase the recruitment of CD11b-positive cells in the tumor sites, which include granulocytes and macrophages." (PMID 22054049, 2011). "Activation of the transcription factors STAT1/STAT3 is crucial in determining whether inflammation in the tumor microenvironment promotes or inhibits cancer development." (PMID 21931823, 2011). "Finally, since STAT3 has been reported to interact and synergize with NF-κB in tumor cells, this study also addresses the functional interplay of NF-κB and decoy ODN." (PMID 21486470, 2011). "Among the genes participating in the cascade of signal transfer in cell activated by leptin, the following ones: AKT1, STAT3, MCL1 were qualified as differentiating stage I and II and VEGFC, CCNDI the encoding genes respectively as differentiating III and IV stage neoplasm." (PMID 22363883, 2011). "Consistent with this study, we also found STAT3 activation in tumor cell." (PMID 22136659, 2011). "In addition to its roles in angiogenesis, tumor invasion, apoptosis, and maintenance of tumor stem cells, STAT3 is known to act as a potent inhibitor of both innate and adaptive immune responses." (PMID 22190972, 2011). "Prophylactic intervention reversed tumor-suppressed phosphorylation or expression of STAT1 (1.82±0.20 vs. 0.46±0.10, p<0.001) and SOCS1 and suppressed the tumor-induced phosphorylation or expression of STAT3 (0.72±0.24 vs. 3.74±1.07, p<0.05) and SOCS3 in the lung tissues." (PMID 21931823, 2011). "Repression of Necdin expression by STAT3 may play an important role in regulating the cell cycle and proliferation in human cancer cells, which has the potential to give tumor cells a growth advantage." (PMID 22046235, 2011).
tumor (continued). "However, STAT1 is the major effector of IFNγ, which is antiproliferative or tumoricidal in several cancer cell types; although STAT3-decoy ODN has been found to induce tumor cell death in several different cell systems, it can also inhibit STAT1." (PMID 21486470, 2011). "STAT3 may also promote tumor cell transformation via anti-apoptotic signaling (i.e., by up-regulating the genes that counteract active cell death)." (PMID 22177381, 2011). "Another important transcriptional activator that controls GSC maintenance and is also important in myriad other signaling pathways in GBM cells that control angiogenesis, tumor cell invasion, apoptosis and immunosuppression, is signal transducer and activator of transcription 3 (STAT3)." (PMID 22030012, 2011). "In addition, the existence of EGFR independent signaling for Stat3 activation has been reported, enhancing the importance of Stat3 activation in tumor growth." (PMID 21197106, 2011). "We next examined whether down-regulation of Necdin occurred in human tumor cells with activated STAT3." (PMID 22046235, 2011). "It is possible that the anti-tumor effects of JSI-124 could be explained by the inhibition of the constitutively activated STAT3 signaling pathway in leukemia." (PMID 21702955, 2011). "STAT3 can trap constitutively activated NF-κB within the nucleus of tumor cells." (PMID 21486470, 2011). "STAT3 signaling within the tumor microenvironment induces the protumor cytokine, IL-23, while inhibiting a central antitumor cytokine, IL-12, thereby shifting the balance of tumor immunity toward carcinogenesis." (PMID 21943203, 2011). "Thus, its constitutive activation in tumor cells points to STAT3 as a valuable target for attacking tumor cells." (PMID 21486470, 2011). "STAT3 in tumor infiltrating monocytes also is an attractive target for cancer therapy." (PMID 22136659, 2011). "Furthermore, STAT3 behaves as an oncogene, and is able to transform normal fibroblast cells which can then form tumours in nude mice." (PMID 21152185, 2011). "In addition, Necdin expression in human tumor cell lines is inversely correlated with activation of endogenous STAT3." (PMID 22046235, 2011). "In particular, STAT3 signaling may coordinate the activities of Tregs with other cell populations in the tumor microenvironment, including tumor stem cells." (PMID 22190972, 2011). "This aberrant STAT3 activation correlates with the tumor grades and clinical outcomes." (PMID 21906308, 2011). "Overexpression of STAT3 in tumor cells can recruit tumor-infiltrating hematopoietic cells by producing chemotactic factors, resulting in infiltrating inflammatory immune cells and subsequently STAT3 activation in immune cells." (PMID 22136659, 2011). "Moreover the Adv-Stat3(-) engineered MSCs carries anti-sense target complementary DNA to the tumor site and suppresses Stat3 expression and its downstream molecules, thus inhibiting tumor growth and increasing the survival of tumor-bearing mice." (PMID 22054049, 2011). "Furthermore, IL-6 mediated activation of STAT3 in tumor cells results in increases in anti-apoptotic, pro-proliferation, and pro-angiogenic genes." (PMID 22171994, 2011). "In addition, evidence has already emerged to suggest that cancer stem cells express a different immunosuppressive cytokine profile in response to STAT3 blockade than bulk tumor cells." (PMID 22190972, 2011). "Similarly to the IFNγ/STAT1 signaling, STAT3 and IL-10 can form a positively regulatory loop to promote tumor progression and metastasis through sustaining immunosuppressive environment in tumor tissue." (PMID 21931823, 2011). "Even if the correct patients are identified, the tumor microenvironment may pose a number of additional challenges to effective GBM therapy with STAT3 blockade." (PMID 22190972, 2011). "Finally, studies have also shown that platinum complexes can promote anti-tumor activity by virtue of their ability to inhibit STAT3." (PMID 20576164, 2010).
tumor (continued). "Another study indicated that FGF-2 could directly upregulate MMP-7 gene expression in human tumor cell lines and umbilical vein endothelial cells through AP-1 and STAT3." (PMID 20939893, 2010). "Constitutively activated STAT3 enhances tumor cell proliferation and prevents apoptosis." (PMID 21079774, 2010). "Thus, administration of either neutralizing IL6Rα antibodies or soluble gp130Fc suppressed enterocyte-specific Stat3 activation and proliferation, and reduced tumor incidence." (PMID 20478049, 2010). "Persistent activation of STAT3, most prominently observed in the epithelial and immune cells that constitute the tumour invasive front, often results from autocrine and paracrine production of IL6-family cytokines by the tumour and associated stroma." (PMID 20478049, 2010). "Thus, tumour cell lines with constitutive STAT3 phosphorylation and dependent on STAT3 for survival exhibit a strictly STAT3-dependent aerobic glycolytic phenotype, comparable to that observed in the Stat3C/C MEFs." (PMID 21084727, 2010). "However, STAT3 was reported to play a pro-oncogenic or tumor-suppressive role depending on the the genetic background of the tumor." (PMID 20712901, 2010). "Thus, excessive Stat3 activity enforces differentiation into Th17 cells even in the context of Th1 polarising anti-tumour conditions, and genetic interference with the IL6/gp130 pathway selectively blocks Th17 cell polarization." (PMID 20478049, 2010). "The HUVECs that were cocultured with the supernatants from Caki-1 and 786-O cells incubated with WP1066 showed reduced tubular formation, and our pathological assessment of the xenograft tumours showed that WP1066 reduced STAT3 activation and the length of CD34-positive microvessels." (PMID 20461084, 2010). "STAT3 emerges as a central player in determining the switch to aerobic glycolysis, and this in turn can explain why so many biologically distinct tumours are addicted to its activity for continuous survival and growth even though sometimes do not strictly require it for transformation." (PMID 21084727, 2010). "Avicins are novel plant derived metabolites that lower energy metabolism in tumor cells by targeting the outer mitochondrial membrane Avicins dephosphorylated STAT3 in a variety of human tumor cell lines, leading to a decrease in the transcriptional activity of STAT3." (PMID 22069560, 2010). "STAT3 is ubiquitously expressed in most tissues and constitutively activated in many tumor cells." (PMID 24281074, 2010). "Simultaneous targeting of such pathways in tumour cells, perhaps in conjunction with antibody-based strategies to curb cytokine-mediated activation of Stat3 (and NF-κB) in immune cells may hold therapeutic potential." (PMID 20478049, 2010). "The induction of aerobic glycolysis is an important component of STAT3 pro-oncogenic activities, since inhibition of STAT3 tyrosine phosphorylation in the tumour cell lines down-regulates glycolysis prior to leading to growth arrest and cell death, both in vitro and in vivo." (PMID 21084727, 2010). "However, persistent Stat3 activation has been shown to rescue tumor cells from sunitinib-induced cell death and to promote cell proliferation by regulating genes encoding antiapoptotic and proliferation-associated proteins." (PMID 20819239, 2010). "Of the seven human STAT genes, STAT3 has been shown to be activated in a wide variety of human tumors and tumor cell lines and its activation is accompanied by increased expression of important cell cycle and survival regulators, such as cyclin D1, c-myc and survivin." (PMID 20723213, 2010). "Is excessive Stat3 activation in epithelial cells sufficient to trigger de novo tumour formation?" (PMID 20478049, 2010). "We show here that constitutively active STAT3 acts as a master regulator of cell metabolism, inducing aerobic glycolysis and down-regulating mitochondrial activity both in primary fibroblasts and in STAT3-dependent tumour cell lines." (PMID 21084727, 2010).
tumor (continued). "STAT3 is activated by cytokines, growth factors and oncogenes, and is constitutively tyrosine-phosphorylated in a high percentage of tumours and tumour-derived cell lines of both liquid and solid origin, where its inhibition often triggers growth arrest and/or cell death." (PMID 21084727, 2010). "Further, blockade of SRC or STAT3 induces apoptosis and tumor regression." (PMID 24281185, 2010). "Furthermore, constitutively activated Stat3 pathway correlates with malignant tumor phenotype, resistance to chemotherapeutic drugs, and poor prognosis in some cancers." (PMID 20459702, 2010). "The preclinical observations cited above suggest that the growth and maintenance of many tumours, including some that are not caused by aberrant activation of Stat3, have become addicted to its continuous activation." (PMID 20478049, 2010). "Importantly, elevated levels of STAT3 phosphorylation were correlated with the tumor invasion, metastasis, and worse prognosis in colorectal, hepatocellular and other carcinoma." (PMID 20712901, 2010). "Importantly, the observation that treatment with the S3I STAT3 inhibitor lowers glucose uptake by tumours prior to arresting their growth, suggests that a similar mechanism for STAT3 addiction occurs in vivo as well." (PMID 21084727, 2010). "We next performed immunohistochemical analysis of Caki-1 xenograft tumours to examine whether WP1066 inhibited its growth by inactivating STAT3." (PMID 20461084, 2010). "We propose that this central metabolic role played at multiple levels may be at the core of the addiction for STAT3 shown by so many biologically different tumours." (PMID 21084727, 2010). "We also tested the hypothesis that the level of p-STAT-3 in a tumor would correlate with the percent of PBMCs displaying p-STAT-3." (PMID 19900287, 2009). "We show here that STAT3 is expressed in both primary SCLC tumour tissues and SCLC cell lines." (PMID 19455144, 2009). "The level of p-STAT-3 in tumor tissue was determined by immunohistochemistry." (PMID 19900287, 2009). "However, there was a significant difference in the levels of activated STAT3 between the normal, benign, borderline and histological grades of tumours, with latter showing the highest levels of expression." (PMID 19088723, 2009). "In this study, we demonstrate that STAT3 is strongly phosphorylated in primary tumour tissues from patients with SCLC indicating that this pathway might be relevant in pathophysiological processes involved in SCLC." (PMID 19455144, 2009). "In addition STAT3 was found to have a profound role in regulating the immune responses in the tumor micro-environment." (PMID 19718269, 2009). "Additionally, Western blotting of protein lysates derived from fresh frozen canine OSA tumor samples revealed STAT3 phosphorylation in 3/8 tumors (38%) as compared to normal canine muscle." (PMID 19284568, 2009). "Stat3, persistently activated in several types of human cancers has been now shown to play a critical role in the process of carcinogenesis by enhancing tumor cell proliferation, survival as well as cellular transformation." (PMID 19440292, 2009). "We now tested whether tumor cells can activate STAT3 within APC using the contact-dependent mechanism, in addition to soluble factors, and compared these two STAT3 activating pathways." (PMID 19718269, 2009). "While Stat3 contributes to oncogenesis, in part, through inhibition of apoptosis, Stat1 is anti-oncogenic; it mediates the apoptotic effects of interferons and contributes to tumor immunity." (PMID 19274102, 2009).